GATA3 (GATA binding protein 3)
Diseases named in the same sentence as GATA3 in open-access papers (continued):
Sharing a sentence is not in itself a finding about the gene and the disease.
breast carcinoma (continued). "Immunohistochemical staining of GATA3 is now used for the diagnostic support of breast cancer and UC as a tumor marker." (PMID 28144859, 2017). "Heterozygous mutations in the GATA3 gene, encoding a transcription factor crucial for breast development, occur in 15% of estrogen receptor-positive (ER+), or luminal-type, breast cancers." (PMID 29262572, 2017). "GATA3 is associated with a less aggressive phenotype and a better prognosis in patients with breast cancer." (PMID 28394898, 2017). "Loss of GATA3 is involved in breast cancer pathogenesis, and a low GATA3 level is associated with higher histological grade, positive lymph nodes and poor prognosis." (PMID 27893417, 2017). "Here we describe the frequently mutated, but poorly studied, breast cancer gene GATA3 as a rare exception: We discover that two different functional classes of mutations in this gene can lead to either gain- or loss-of-function activities." (PMID 27588951, 2016). "The crucial role of GATA3 in the mammary gland is further demonstrated by the observationof GATA3 mutations in ~10% of human breast cancers." (PMID 26953528, 2016). "GATA3 is implicated in breast cancer progression, and recently has been identified as one of the most frequently mutated genes in breast cancer." (PMID 26922637, 2016). "Here, we uncover a similar phenomenon for GATA3, a frequently mutated, yet poorly understood, breast cancer gene." (PMID 27588951, 2016). "For instance, GATA3 is essential for murine mammary gland development and is one of the most frequently mutated genes in human breast cancer, suggesting a tumor suppressor function in the mammary gland." (PMID 27374105, 2016). "Loss of GATA3 expression marks the progression from adenoma to early carcinoma in multiple mouse models of breast cancer development." (PMID 27374105, 2016). "Our findings shed light on the functional consequences of frequent GATA3 mutations in breast cancer and represent a first lead toward personalised therapy for a large subgroup of breast cancer patients." (PMID 27588951, 2016). "GATA3 is one of the most frequentlymutated genes in breast cancer, with 14% of ER+ cases harbouringGATA3 mutations." (PMID 26884552, 2016). "The importance of GATA3 for mammary luminal cell proliferation and differentiation is suggested by the high expression of GATA3 in luminal breast cancers and recurrent mutations in the luminal subtype that stabilize GATA3 protein expression levels." (PMID 26097693, 2015). "ER1, GATA3 and Trps1 are among the genes that are highly expressed in the E13.5 mouse mammary gland and have also been implicated in human breast cancer." (PMID 26215676, 2015). "All were associated with older age at diagnosis, except GATA3, which was independently associated with breast cancer arising in young women (15.2 % versus 8.2 % versus 9 %; P = 0.003, false discovery rate (FDR) = 0.033)." (PMID 26467651, 2015). "GATA3 is frequently mutated in breast cancer and is known to promote luminal cell differentiation in the mammary gland, but has not been previously studied in colon cancer." (PMID 26097693, 2015). "In the present work, we demonstrated that progestin-induced PR activation promotes the loss of GATA3 expression in breast cancer cells through transcriptional and post-translational regulation." (PMID 25479686, 2014).
breast carcinoma (continued). "Among the top ten ranked genes with positive association to ER was the transcription factor GATA3 known to be associated with ER, ER status and hormonal responsiveness in breast cancer." (PMID 24392136, 2014). "To characterize a mutant GATA3-associated signature, we analyzed mutation data of luminal breast cancer patients from The Cancer Genome Atlas." (PMID 25410484, 2014). "Here, we focused on its function in luminal breast cancer, where GATA3 is frequently mutated, and its levels are significantly elevated." (PMID 25410484, 2014). "GATA3 is required for estrogen stimulation of cell cycle progression in breast cancer cells and we showed that this truncating mutation present in MCF7 genome uncouples protein level regulation from hormonal signaling." (PMID 24758297, 2014). "GATA3 is one of the frequently mutated genes in breast cancer, predominantly in the luminal subtype." (PMID 25410484, 2014). "The aim of the present study was to evaluate the effect of a breast cancer-specific mutation in GATA3 on biochemical properties and genomic location of the protein." (PMID 24758297, 2014). "GATA3 is considered to play a dual role in oncogenesis and cancer development, whereas somatic GATA3 mutations have been reported in breast cancer." (PMID 24748983, 2014). "A recent study identified GATA3 as one of the only three genes carrying somatic mutations with more than 10% incidence across breast cancer subtypes defined by the mRNA expression profile." (PMID 25479686, 2014). "Variants of the GATA3 genetic 3′ untranslated region (3′UTR) microRNA (miRNA) binding sites have been associated with breast cancer risk." (PMID 24748983, 2014). "The increase over normal in GATA3 was especially prevalent in patient samples associated with the group 1 cohort, a cohort with reduced overall survival for patients with TN breast cancer." (PMID 24426833, 2014). "We propose that this specific, cancer-derived mutation in GATA3 deregulates physiologic protein turnover, stabilizes GATA3 binding across the genome and modulates the response of breast cancer cells to estrogen signaling." (PMID 24758297, 2014). "In the present study, we reveal that progestin-induced PR activation leads to loss of GATA3 expression in breast cancer cells through transcriptional and post-translational regulation." (PMID 25479686, 2014). "Recent genome-wide studies of Gata3 have mainly focused on the molecular mechanisms underlying its critical roles in T cells and breast cancer." (PMID 25299227, 2014). "We identified further modulations to GATA3 function by altered activity of mutant GATA3, and associated genetic signatures in populations of luminal breast cancer patients." (PMID 25410484, 2014). "The shift in regulatory activity demonstrates opposing tumor suppressor and tumor promoting associated effects of GATA3 in normal and breast cancer cells, respectively." (PMID 25410484, 2014). "GATA-3, in association with estrogen receptor, can regulate genes critical to the hormone-responsive breast cancer phenotype and play a crucial role for the response of estrogen receptor alpha-positive breast cancers to estradiol." (PMID 23516510, 2013). "Another ER interacting partner, GATA3, was found to be highly mutated in all the studies (10.8% of breast cancers in TCGA study), although GATA3 and FOXA1 mutations were mutually exclusive." (PMID 23420418, 2013). "In breast cancer cell lines, GATA-3 has been positively implicated in mediating the estrogen–ER signaling." (PMID 23192763, 2013). "We evaluate FOXA1 and GATA-3 expression in 249 breast carcinomas by immunohistochemistry, associating it with breast cancer molecular markers, clinicopathological features and patient's survival." (PMID 19549328, 2009).
breast carcinoma (continued). "Our results highlight the role of estrogen-signaling pathways (mainly CYP19/aromatase, GATA3, and ER-β) in the risk of locoregional recurrence of breast cancer in young women." (PMID 19638208, 2009). "The present results highlight the role of estrogen-signaling pathways, mainly CYP19/aromatase, GATA3, and ERβ, in the risk of recurrence in young women with breast cancer." (PMID 19638208, 2009). "The aim was to test, for the first time, the possible utility of FOXA1 and/or GATA-3 as classifiers for breast cancer recurrence in this high-risk subset of patients, revealing a stratification of ER-negative tumours with different biological behaviours." (PMID 19549328, 2009). "Microarray analyses have revealed that forkhead box A1 (FOXA1) and GATA binding protein 3 (GATA-3) are expressed in close association with ERα, both encoding for transcription factors with a potential involvement in the ERα-mediated action in breast cancer." (PMID 19549328, 2009). "In this sense, the loss of differentiation factors has already been implicated in late stages of tumor progression as with GATA-3 (ENSG00000107485) in breast cancer." (PMID 19243219, 2009). "Previous work using immunohistochemistry has shown that the expression of FOXA1 and of GATA-3 is in close association with ERα expression in breast cancer, highlighting their prognostic and predictive value in this malignancy." (PMID 19549328, 2009). "GATA3 expression was also highly associated with estrogen receptor and progesterone receptor status (p = 0.0001) and tumor grade (p = 0.004) in breast carcinomas." (PMID 17078870, 2006). "GATA3, a zinc finger transcription factor, is a master regulator of Th2 cell differentiation and immune activation, and is also implicated in the pathogenesis of several diseases, including asthma, breast cancer, and certain leukemias." (PMID 41495895, 2026). "However, unlike FOXA1, this indirect down-regulation of ER level, caused by competition between FOXC1 and GATA3, cannot inhibit the progression of breast cancer." (PMID 40003882, 2025). "Therefore, the associations we report with ER-negative breast cancer genes and African ancestry should be taken with caution, but the associations we reported with ER-positive related breast cancer genes (e.g., GATA3, FGFR1) are likely correct." (PMID 41162424, 2025). "As tumor and plasma genomic profiling are becoming available to a wider population of patients via universal genomic testing initiatives, we may further define the genomic landscape of GATA3 mutations in breast cancer." (PMID 40439821, 2025). "Gene Set Enrichment Analysis (GSEA) of both situations relative to control breast cancers expressing GATA3, highlighted shared associated gene expression signatures, including cancer aggressiveness and cell proliferation, confirming that GATA3 is indeed a powerful tumour suppressor gene." (PMID 40585280, 2025). "Numerous sequencing analyses have shown that GATA3 gene mutations are common in breast cancer." (PMID 40439821, 2025). "Among 121 patients with breast cancer, 10 patients had a single GATA3 mutation." (PMID 40439821, 2025). "Future research should further explore the molecular mechanisms of GATA3 in breast cancer to better elucidate the specific association between GATA3 expression and the biological behavior of the disease, thereby providing more robust evidence for personalized treatment." (PMID 40881878, 2025). "This appears to be a new finding compared to an earlier study of GATA3 mutations in familial breast cancer, where GATA3 mutations were found in 22% (7/32) of patients without BRCA1/1 mutations and not identified in patients with germline BRCA1 or BRCA2 mutations (n = 0/23)." (PMID 40439821, 2025). "Additionally, the transcription factor GATA-3 has been linked to favorable prognostic factors and survival rates in canine mammary tumors, with higher expression correlating with well-differentiated tumors and the expression of estrogen receptors." (PMID 40286049, 2025).
breast carcinoma (continued). "Moreover, GATA2 expression is associated with more, rather than less, aggressive prostate cancer, with overexpression increasing metastatic capacity, while GATA3 is associated with less aggressive breast cancer and overexpression prevents metastasis." (PMID 38317241, 2024). "For instance, reduced GATA3 expression in breast cancer is linked to a poorer prognosis." (PMID 39768217, 2024). "Although GATA3 is a powerful diagnostic marker for breast cancer, its utility may be limited by the heterogeneity of breast cancer subtypes." (PMID 39768217, 2024). "GATA3 is the third most mutated gene in luminal breast cancer." (PMID 39242600, 2024). "Dysregulation of GATA3 has also been associated with other diseases, including breast cancer, where reduced GATA3 expression was linked with a poorer prognosis and unfavorable tumor phenotype, and where mutations in exon 6 of GATA3 were detected in >50% of tested patients." (PMID 37377909, 2023). "Recent findings have suggested that immunohistochemical stain for trichorhinophalangeal syndrome type 1 (TRPS1) is a more sensitive and specific marker than GATA3 for breast carcinoma, and TRPS1 is especially useful as a diagnostic tool for triple‐negative breast cancers." (PMID 36281523, 2023). "In breast cancer, GATA3 is associated with tumor differentiation and recurrence." (PMID 37629741, 2023). "Low GATA-3 expression is a significant risk factor for death in women with breast cancer." (PMID 37483298, 2023). "Notably, we previously demonstrated that the expression of FRA1 is elevated and EMT is activated in Gata3 deficient breast cancers." (PMID 37353480, 2023). "Mutations in GATA3, which is involved in normal mammary gland development and has been previously associated with ER positivity, occur frequently in breast cancer, in particular frameshift indels and were strongly enriched in a cohort of Nigerian breast cancer patients." (PMID 37919776, 2023). "GATA3 mutations are almost always associated with breast cancer compared to other cancers." (PMID 35846378, 2022). "Recent large-scale molecular profiling of breast carcinomas identified frequent mutations in GATA3." (PMID 35154280, 2022). "In addition, GATA3 mutations are frequently observed in several breast cancer clinical cases and most of those mutations are associated with GATA3 loss of function." (PMID 35804829, 2022). "We, therefore, hypothesized that GATA3 loss may induce addiction to mTOR signaling in breast cancer cells." (PMID 35440675, 2022). "Clinical data suggest that different types of GATA3 mutations may have distinct roles in breast cancer characterization." (PMID 35154280, 2022). "GATA3 is known to be one of the most frequently mutated genes in breast cancer." (PMID 35154280, 2022). "We hypothesized that MDM2 inhibition may represent an alternative therapeutic strategy in endocrine therapy-resistant breast cancers harboring GATA3 mutations." (PMID 35440675, 2022). "In breast cancer, Gata3 expression is associated with invasive growth and poor prognosis." (PMID 34195082, 2021). "Besides the different associations of GATA3 with different forms of breast cancer, GATA3 has been associated with hypoparathyroidism, deafness, and renal dysplasia (HDR) syndrome." (PMID 34815386, 2021). "Additionally, in the multivariable logistic regression analysis, age at diagnosis, tumor size (pT), PR status, and histological tumor type were found to be independently associated factors of GATA3 mutation status in breast cancer." (PMID 33462316, 2021). "Remarkably, GATA3 labeling was preserved in paired metastases and all “luminal loss” metastases that have lost ER and/or PR expression, indicating the application of this marker for diagnosis of metastatic breast cancers." (PMID 34094972, 2021). "High expression of GATA3 is associated with good prognosis of ER+ breast cancer." (PMID 34109184, 2021).
breast carcinoma (continued). "Taking this advantage in our study, we demonstrated that haploid loss of Gata3 in p18 deficient background converts well-differentiated mammary tumors into poorly-differentiated mammary tumors with the activation of EMT and promotes tumor initiating and metastatic potential." (PMID 34373738, 2021). "Interestingly, Moonlight detected GATA3 as an oncogene in breast cancer with several mutated samples: frameshift insertion, deletion, and splice site." (PMID 31900418, 2020). "Interestingly, Moonlight identified GATA3 with three different mutation sites and predicted it correctly as an oncogene in breast cancer." (PMID 31900418, 2020). "Initial studies suggested that GATA3 is relatively sensitive and specific for tumors of breast or urothelial origin, and the downregulation of GATA3 has also been found to be associated with a poor prognosis of breast cancer." (PMID 31636361, 2020). "Together, our results may suggest that GATA3 mutations have a higher prevalence breast cancer patients younger than 40 years than those between 40 and 45 years." (PMID 32164620, 2020). "However, our results are consistent with a study performed on mice demonstrating that the loss of GATA3 expression is associated with mammary tumors with a high grade of malignancy." (PMID 32225066, 2020). "Mutations in GATA3 have also been identified in a subset of breast cancers." (PMID 31408468, 2019). "On the contrary, other studies have reported that loss of GATA-3 expression, a master transcriptional regulator of Th2 specific cytokines, has been associated with aggressive tumor phenotype and worse prognosis in breast cancer patients." (PMID 31145753, 2019). "GATA3 is a transcription factor frequently mutated in breast cancer and thought to be an oncogene." (PMID 31294536, 2019). "GATA3 loss is associated with aggressive breast cancer development, but the mechanism by which breast cancer is affected by the loss of GATA3 function remains unclear." (PMID 31685800, 2019). "Modulation of GATA3 by ZBTB32 in turn caused the development of aggressive breast cancers." (PMID 31787845, 2019). "GATA3, specifically, has been identified as a critical component of mammary epithelial cells development and is 1 of 3 genes that have been shown to be mutated in > 10% of breast cancers." (PMID 29378668, 2018). "GATA3 is frequently mutated in breast cancer; these mutations are widely presumed to be loss-of function despite a dearth of information regarding their effect on disease course or their mechanistic impact on the breast cancer transcriptional network." (PMID 29535312, 2018). "In addition, low expression of GATA3 was associated with a poor survival rate and more aggressive disease, whereas GATA3-expressing breast cancer patients had a better prognosis, were less likely to relapse, and had a better overall survival rate." (PMID 30463912, 2018). "Collectively, such data indicate that GATA-3, function as a tumor suppressor, may emerge as a potential biomarker to detect and predict risk of breast cancer development." (PMID 30100605, 2018). "Recent large-scale breast cancer genomic profiling identified frequent mutations in the GATA3 gene." (PMID 29535312, 2018). "ERα-positive tumours display a more differentiated phenotype and are generally less aggressive, which may be another reason why GATA3 expression in breast cancer is associated with a more favourable prognosis." (PMID 30463912, 2018). "Recently, GATA3 overexpression has been reported to be associated with poor overall survival in Peripheral T-cell lymphoma, but a favorite prognostic factor for breast cancer." (PMID 28415601, 2017). "Datasets of GATA3 and P300 from the T47D breast cancer cell line are also linked to FOXA." (PMID 27899659, 2017). "Therefore, MCF-7 is a relevant model to understand the functional consequences of GATA3 truncating mutations that occur almost exclusively in ER+ breast cancers." (PMID 29262572, 2017).